INS (insulin)
Diseases named in the same sentence as INS in open-access papers (continued):
Sharing a sentence is not in itself a finding about the gene and the disease.
Alzheimer disease (continued). "Based on this logic, protein traffic vesicles, oncogenes, gonadotropin hormones and insulin-related pathway were identified as potential players in early Alzheimer’s disease." (PMID 24196233, 2013). "In a clinical study, insulin was administered to Alzheimer’s disease patients to improve their cognitive functions, given the neuroprotective properties of insulin." (PMID 24202332, 2013). "Thus, impaired insulin signaling and subsequent decrease in brain glucose uptake (leading to disturbances in bioenergetics) and compromised synaptic plasticity (leading to disturbances in synaptic transmission) are major deficiencies associated with Alzheimer’s disease." (PMID 23875003, 2013). "Further studies have demonstrated that intranasal insulin improves verbal memory in both cognitively impaired older adults and those with early Alzheimer disease (AD)." (PMID 23135822, 2013). "Dysregulation of insulin secretion or insulin receptor signaling has also been reported in serious mental illnesses, such as Alzheimer's disease." (PMID 22348066, 2012). "This provides a link between mitochondrial dysfunction and insulin resistance that is highly prevalent in ageing and Alzheimer’s disease (AD)." (PMID 23730255, 2012). "Cerebrospinal fluid (CSF) of people with Alzheimer's disease has lower concentrations of insulin, as compared with controls." (PMID 22389813, 2011). "The concept that impaired insulin signalling influences neurodegenerative mechanisms in Alzheimer's disease (AD) and leads to impairment in cognitive processes is attracting increasing attention." (PMID 21347323, 2011). "As impaired insulin signalling (IIS) is a risk factor for Alzheimer’s disease we crossed mice (Tg2576) over-expressing human amyloid precursor protein (APP), with insulin receptor substrate 2 null (Irs2−/−) mice which develop insulin resistance." (PMID 19523444, 2009). "Intranasal insulin improves memory, attention, and functioning in patients with Alzheimer's disease or mild cognitive impairment, and even improves memory and mood in normal adult humans." (PMID 19091002, 2008). "This study investigated the regulatory role of the long non-coding RNA maternally expressed gene 3 (MEG3) in tau hyperphosphorylation and insulin signaling (PI3K/AKT1/GSK3β) under high-glucose (HG)-induced neurotoxic conditions mimicking Alzheimer’s disease pathology." (PMID 40869265, 2025). "The combined effect of systemic inflammation, BBB transport dysfunction, and direct lipid-mediated neuronal injury therefore establishes a pathogenic feedback loop that reinforces and accelerates a brain insulin resistance and contributes to Alzheimer’s disease progression." (PMID 41294899, 2025). "Metabolic dysfunction contributes to the risk and progression of Alzheimer’s disease (AD) through insulin signaling, but the cellular mechanisms are not fully understood." (PMID 40964391, 2025). "Impairment of the intracellular insulin signaling pathway plays a critical role in the pathogenesis of Alzheimer’s disease, as insulin may indirectly enhance the cleavage of APP due to controlling the γ-secretase complex, increasing the level of Aβ." (PMID 39859258, 2025). "The authors studied the effect of DNJ treatment on insulin signaling and Alzheimer’s disease markers in human insulin-resistant SK-N-SH neuroblastoma, underlying the usefulness of DNJ, which attenuated tau and amyloid pathologies by reversing neuronal insulin resistance." (PMID 40807388, 2025). "On the other hand, there are results from other studies which indicate that dysfunctional mitochondria in diabetic patients may also interact with impaired insulin signaling in these patients, stimulating the development of Alzheimer’s disease." (PMID 39859258, 2025). "However, dysfunction of insulin signaling in the aging brain leads to abnormal energy metabolism, brain insulin resistance, and dementia, as observed in Alzheimer’s disease (AD)." (PMID 40283962, 2025).
Alzheimer disease (continued). "Elevated blood glucose levels in patients with Alzheimer's disease may reflect impaired cerebral glucose uptake or peripheral insulin resistance, both of which are well-documented contributors to Alzheimer's disease pathogenesis and oxidative stress." (PMID 41260101, 2025). "In fact, insulin plays pivotal roles in neuronal survival, synaptic plasticity, and memory/learning processes and it is well-established that insulin resistance has direct implications in the pathogenesis of Alzheimer’s disease (AD)." (PMID 41302504, 2025). "In addition to the classically accepted pathophysiological features of Alzheimer’s disease (AD), increasing attention is paid to the role of the insulin-resistant state of the central nervous system." (PMID 40430434, 2025). "The expression of miR-7 is increased in the brains of patients with Alzheimer’s disease (AD) and with resistance to insulin, as it targets crucial regulators of insulin homeostasis and also key cholesterol biosynthesis elements essential for forming lipid rafts." (PMID 38338859, 2024). "Together, these findings from NP-based and [18F]-insulin studies propose innovative nasal delivery systems for insulin, providing a solid foundation for further clinical evaluation and potential treatment of Alzheimer's disease." (PMID 39267777, 2024). "Interestingly, in Alzheimer’s disease, there are a reduced number of receptors in the brain for insulin, and there is also the phenomenon of brain insulin resistance." (PMID 39458564, 2024). "Thus, T3 normalized the expression of proteins in the insulin signaling pathway in the hippocampus, emphasizing the potential neuroprotective role of T3 in Alzheimer’s disease, which aligns with the literature." (PMID 39513900, 2024). "In Alzheimer’s disease, the increase in ROS induces the expression of pro-inflammatory genes, and oxidative stress and pro-inflammatory factors decrease insulin secretion and disrupt insulin signal transduction, respectively." (PMID 38611418, 2024). "The cognitive enhancement provided by insulin in both healthy and diseased individuals, as well as its various positive effects on conditions such as dementia and Alzheimer’s disease, is related to its direct impact on the cerebellar and hippocampal regions of the brain through IN administration." (PMID 39329976, 2024). "Furthermore, the central actions of insulin are potentially desirable in Alzheimer’s disease, traumatic brain injury and cerebral ischemia." (PMID 39458599, 2024). "Moreover, these authors reported a reduction in Aβ accumulation and suggested that M. nigra mitigates Alzheimer’s disease by activating the DAF-16 insulin signaling pathway, which is involved in the oxidative stress response, in C. elegans." (PMID 39200504, 2024). "Enrichment analysis by the DAVID dataset was employed and highlighted the SPP1 as a novel target, with its receptor CD44 playing a significant role in the inflammatory cascade and disruption of insulin signaling, contributing to the neurodegenerative aspects of Alzheimer’s disease." (PMID 38809924, 2024). "From this perspective, the therapeutic potential of irisin requires further investigation, particularly regarding its role in brain insulin resistance, which may act as an additional pathogenetic factor in Alzheimer’s disease." (PMID 39769243, 2024). "Since glucose hypometabolism is one of the early and persistent signs of Alzheimer's disease, along with the fact that Alzheimer's brains possess impaired insulin signaling, icv STZ injections are used by some researchers to test pharmacological therapies for AD in preclinical settings." (PMID 38769074, 2024).
Alzheimer disease (continued). "In addition to the hippocampus, the significance of insulin expression in the CNS in the context of Alzheimer’s disease was documented in the cerebral cortex as well." (PMID 37047558, 2023). "In addition to their role in protein aggregation and synaptic health, GLP-1 receptor mimetics have displayed the capacity to improve insulin sensitivity, a critical factor in the context of Alzheimer’s disease." (PMID 38002034, 2023). "Human studies involving patients with mild cognitive impairment and Alzheimer’s disease have shown that the administration of certain antidiabetic drugs, such as intranasal insulin, metformin, incretins and thiazolidinediones, can improve cognitive function and memory." (PMID 37968954, 2023). "Conversely, excitation of specific signaling pathways in A2 astrocytes can improve cognitive impairment; for example, insulin therapy was shown to enhance the mental competence of patients with Alzheimer’s disease due to insulin receptor activation on A2 astrocytes." (PMID 36902058, 2023). "The causal influence of sarcopenia on cardiometabolic disease and Alzheimer's disease and whether and to what extent insulin resistance plays a mediating role therein were unclear." (PMID 37403750, 2023). "Women in the lowest tertile of fasting insulin showed a higher prevalence of the APOE-4 allele compared to women with higher insulin, which is remarkable as the APOE-4 allele is the strongest genetic risk factor for dementia, particularly Alzheimer’s disease." (PMID 37420130, 2023). "Moreover, insulin concentration is reduced in the CSF of patients with Alzheimer’s disease, while decreased insulin levels were found post-mortem in the brain parenchyma of patients who suffered from sporadic Alzheimer’s disease." (PMID 37047558, 2023). "Emerging evidence indicates that insulin dysregulation could influence the clearance of the amyloid β peptide and phosphorylation of tau, which are hallmarks of Alzheimer's disease." (PMID 37403750, 2023). "In Alzheimer’s disease, impaired insulin signaling could inhibit the PI3K/AKT pathway and lead to neurodegeneration by increasing oxidative stress, apoptosis, mitochondrial dysfunction and necrosis." (PMID 37610708, 2023). "Since then, IN administration of insulin aqueous solutions has been extensively studied in various preclinical and clinical trials for the treatment of Alzheimer’s disease, mild cognitive impairment, diabetes, insulin resistance, and Parkinson’s disease, among other conditions." (PMID 38258077, 2023). "Furthermore, the influence of insulin dysfunction on Alzheimer’s disease (AD) pathogenesis has been underscored by studies involving mice with streptozotocin-induced (STZ) type I diabetes." (PMID 38002034, 2023). "Recent study reported insulin modulates clearance of Aβ through its effects on lipid metabolism and proteases, and peripheral insulin resistance might precede Aβ accumulation, as the pathological processes of Alzheimer's disease." (PMID 36875407, 2023). "A detailed study of the role of brain insulin in the etiology and pathogenesis of the nervous and endocrine diseases led to the concept that the widespread neurodegenerative disease, Alzheimer’s disease (AD), is another form of diabetic pathology, referred to as type 3 diabetes." (PMID 36834685, 2023). "Additionally, insulin formulations have shown effectiveness in improving the cognition of adults with mild cognitive impairment or early-stage Alzheimer’s disease." (PMID 36834804, 2023). "Phase 2 and 3 controlled trials have been recently completed, investigating the efficacy of two IN insulin devices (ViaNase by Kurve Technology and I109 Precision Olfactory Delivery by Impel NeuroPharma) on patients with mild cognitive impairment or Alzheimer’s disease over 18 months." (PMID 36834804, 2023). "In addition, the Alzheimer disease (AD) pathway, Parkinson disease (PD) pathway, and insulin signaling pathway were present only in wt-GISTs in comparison to mu-GISTs." (PMID 36828845, 2023).
Alzheimer disease (continued). "Moreover, Alzheimer’s disease dementia patients showed impaired insulin signaling in the brain, which is considered an early stage of cognitive deficit." (PMID 35328405, 2022). "Moreover, in trials of both healthy adults and patients with Alzheimer’s disease or cognitive impairment, intranasal administration of insulin versus placebo improved recall significantly." (PMID 35745751, 2022). "Further, insulin mRNA transcripts were detected in human post-mortem brain tissue, and reduced levels were found in the hippocampus and hypothalamus of individuals who had Alzheimer’s disease (AD)." (PMID 35741464, 2022). "More interestingly, patients with diabetes often exhibit pathologic changes similar to those seen in early Alzheimer’s disease (AD; Ninomiya, 2014), and the mechanism may involve immunity, inflammation, and insulin resistance." (PMID 36185492, 2022). "Similar to Alzheimer’s disease, pathological alterations in insulin occur years before individuals get to know about type 2 DM, which generally occurs once pancreatic beta cell malfunction and resistance to insulin develop chronic high blood sugar levels." (PMID 36258952, 2022). "The mediators regulating this transport are yet to be discovered and described, but the existing load of evidence suggests that inflammation, diabetes and triglycerides enhance insulin transport to the CNS, while aging, obesity, fasting and Alzheimer’s disease weaken it." (PMID 35454152, 2022). "Accordingly, insulin has been emphasized as a therapeutic drug for Alzheimer’s disease." (PMID 35558436, 2022). "Kyoto Encyclopedia of Genes and Genomes (KEGG) analysis revealed that Huntington’s diseases, Alzheimer’s disease, Parkinson’s disease, dopaminergic synapse signaling pathway, glioma, and insulin signaling pathway were among the most affected pathways in PFC and NAc." (PMID 36582489, 2022). "Thus, Alzheimer’s disease (CUI: C0002395) is chosen asthe primary target to three diverse sources: insulin (CUI: C0021641),hypothyroidism (CUI: C0020676), and amyloid (CUI: C0002716)." (PMID 35936510, 2022). "PTP-1B, a regulator of insulin and leptin signalling that has been shown to be involved in multiple Alzheimer's disease processes, was moderately increased in both Dem-Alzheimer's disease (fold-change = 1.39, P = 0.037) and Dem-Other (fold-change = 1.39, P = 0.023) compared with CN individuals." (PMID 35800899, 2022). "Interestingly, seven of the pathways regulated by the miRNA target genes were in common with the pathways regulated by the differentially expressed protein coding mRNAs, including insulin signaling, regulation of actin cytoskeleton, and Alzheimer’s disease." (PMID 36361847, 2022). "The intranasal administration of an insulin aqueous solution has also been widely studied in up to Phase 2/3 clinical trials, as a therapy for Alzheimer’s disease, mild cognitive impairment, diabetes, insulin resistance, and Parkinson’s disease, among other conditions." (PMID 34731414, 2022). "We propose that the appearance of abnormal tau might potentiate the toxic environment by interfering with the insulin signaling cascade in the brain of patients with Alzheimer’s disease." (PMID 35264925, 2022). "Human clinical trial outcomes following intranasal insulin intervention in Alzheimer’s Disease." (PMID 36555450, 2022). "Additionally, metabolism was affected, appearing as altered metal iron homeostasis, a feature of Alzheimer’s disease and increased glucose metabolism and insulin-glucose signaling, a feature of senescence." (PMID 36408415, 2022). "Over the past 16 years, many researchers have proposed alterations in insulin levels or insulin signaling in people with late-onset Alzheimer's disease, recommending that people with Alzheimer's disease experience increased insulin levels and resistance to insulin in the brain." (PMID 36258952, 2022).
Alzheimer disease (continued). "Increasing evidence shows that the disturbance of insulin signalling in the brain may contribute to the pathophysiology of Alzheimer’s disease." (PMID 35802659, 2022). "In addition, recent findings demonstrated that reduced BVR-A levels or impaired BVR-A activation contribute to the development of brain insulin resistance and metabolic alterations in Alzheimer’s disease." (PMID 35628384, 2022). "The therapeutic effects of tES on brain metabolism are relevant in dementia since the early stage of Alzheimer's disease (AD) shares molecular and cellular features, including insulin resistance and mitochondrial dysfunctions, where AD has been called “type 3 diabetes”." (PMID 36698881, 2022). "Interestingly, the amount of insulin was found to be decreased in the post-partum brains of Alzheimer's disease patients." (PMID 34877187, 2021). "Insulin is also known to improve cognition in rodent models of Alzheimer’s disease." (PMID 34449653, 2021). "Briefly, we propose that chronic sleep restriction may induce the most common neurodegenerative disease worldwide Alzheimer’s disease (AD), by impairing brain insulin signaling." (PMID 34539357, 2021). "The top 20 significant terms of the KEGG analysis included endocytosis, Alzheimer's disease, the spliceosome, the mTOR signaling pathway, RNA transport, insulin resistance, autophagy, and the Notch signaling pathway, and these pathways were associated with HSF1." (PMID 34239690, 2021). "In one of the recent mini-reviews it is emphasized that targeting insulin resistance may be a breakthrough strategy to treat Alzheimer’s disease." (PMID 34769198, 2021). "Moreover, intranasal insulin promotes memory function in healthy, mild cognitive impairment, and advanced Alzheimer's disease patients." (PMID 34877187, 2021). "The long-acting insulin analogue Detemir (21 days, 40 IU/patient/day) significantly improved memory in patients with Alzheimer’s disease and moderate cognitive deficits, but its improving effect with prolonged use (2–4 months) at the same daily dose disappeared." (PMID 34769198, 2021). "These apparent contradictory results can be explained by the fact that GHR signaling regulates insulin sensitivity and there is plenty of evidence indicating that brain insulin action plays a major role in regulating memory and is likely involved in the pathophysiology of Alzheimer’s disease." (PMID 33440789, 2021). "Therefore, an idea has been proposed that Alzheimer’s disease can be an “insulin-resistant state” or even a “type 3 diabetes”." (PMID 34360906, 2021). "Furthermore, insulin can specifically accumulate into the hippocampus, which is involved in neurodegenerative disorders such as Alzheimer’s disease." (PMID 34834159, 2021). "In addition, 120-day administration of 20 IU or 40 IU insulin in 104 participants showed that both doses improved performance on the Alzheimer’s Disease Assessment Scale-Cognitive subscale (ADAS-Cog12), a measure of global cognition." (PMID 34576151, 2021). "Insulin/IGF-I signaling deficient mice report a delayed onset of fatal malignancies, increased insulin sensitivity, and a reduction in age-dependent cognitive impairment, including protection from Alzheimer’s disease (AD)-like associated pathologies." (PMID 34067055, 2021). "Alzheimer’s disease is thought to involve insulin resistance and glucose hypo-metabolism, but it is debatable whether these factors are triggers for neurodegeneration." (PMID 33536868, 2020). "Although we hypothesized that MET could improve memory dysfunction in Alzheimer’s disease patients by enhancing insulin sensitivity and signaling, we observed that chronic treatment with MET alone actually induced cognitive deficits in rodents." (PMID 32156040, 2020).